RN7SKP150 (RN7SK pseudogene 150)
Gene: Miscellaneous RNA gene on chromosome 5 (179,845,832 to 179,846,152, forward strand). Ensembl gene ENSG00000222448.
Homologues: Orthologues: chimpanzee 7SK (93% identical). Paralogues in human: 7SK (73% identical), RN7SKP79 (72% identical), RN7SKP250 (72% identical), RN7SKP294 (72% identical), RN7SKP71 (72% identical), RN7SKP176 (72% identical), RN7SKP203 (71% identical), RN7SKP180 (71% identical), RN7SKP217 (71% identical), RN7SKP87 (71% identical), RN7SKP161 (70% identical), RN7SKP189 (70% identical), and 284 more.